JAK1 (Janus kinase 1)
Diseases named in the same sentence as JAK1 in open-access papers (continued):
Sharing a sentence is not in itself a finding about the gene and the disease.
cancer (continued). "While analyzing multiple cancer disorders, we found highly variable expression among genes implicated in cancer: EEF1A1, GNAS, NPM1, PIM1, and RHOA are known oncogenes; H3F3A, PTPRC, SMARCB1, and B2M are possible oncogenes; and CASP8, JAK1, and PRKAR1A are known tumor suppressor genes." (PMID 34174938, 2021). "Similarly, ruxolitinib inhibits the influenza prey protein JAK1, a part of the pathways in cancer gene-set." (PMID 33720009, 2021). "Therefore, JAK1 inhibitors combined with additional target inhibitors are under investigation for treatment of various types of cancers." (PMID 33523587, 2021). "However, the lack of ruxolitinib effect on CT26 cell invasiveness suggested that cancer cells are able to circumvent the inhibition of JAK1/2 using an alternative pathway." (PMID 33923020, 2021). "For example, although anti-PD1 therapy is an effective cancer treatment, the overexpression or mutations of LAMA3, CXCR2, and JAK1/2 could prevent the immune system from boosting effective antitumor immunity." (PMID 34660300, 2021). "In the pathogenesis of cancer, elevated IL‐6 and IL‐27 could stimulate the activation of JAK1 and JAK2 enzymes, which subsequently mediate tyrosine phosphorylation of STAT3 at Tyr705." (PMID 33277798, 2021). "Therefore, our findings suggest that Anwulignan can inhibit NSCLC cancer growth by inhibiting the JAK1/STAT3 signalling pathway." (PMID 33523587, 2021). "Interestingly, a combination consisting of trastuzumab and ruxolitinib – a JAK1/JAK2 inhibitor – demonstrated a synergistic cancer inhibition in mouse xenografts of HER2 transformed BC cell lines." (PMID 33193699, 2020). "This study showed that BTZ@HMSNs further increased the mRNA level of SHP-1 as well as reduced the mRNA levels of c-Kit, NF-κB, and JAK1, which indicated that the anti-cancer effect of BTZ@HMSNs might be related to SHP-1/c-Kit/NF-κB/JAK1 pathway." (PMID 33290262, 2020). "In addition, somatic mutations in cancer cells, including loss-of-function mutations in JAK1/2, APLNR, PTPN2, and PBRM1, significantly correlate with the efficacy of cancer immunotherapies." (PMID 32244804, 2020). "Overall, these results suggest that the expression of JAK1 is decreased in various types of cancer, particularly in LUAD, demonstrating that JAK1 may suppress LUAD tumorigenesis." (PMID 33323549, 2020). "In carcinoma-associated fibroblasts, DNMT3B methylated CpG sites of the promoter of SHP-1 phosphatase and abrogated SHP-1 expression, leading to constitutive phosphorylation of JAK1." (PMID 32895373, 2020). "Clinical trials testing Janus kinase-1 (JAK1) inhibitors in cancers are under way." (PMID 31790361, 2019). "A potential mechanism would be that mutations in JAK1/JAK2 might block PD-L1 induction, protecting cancer cells from immune attack." (PMID 30670049, 2019). "The extensive inhibition of JAK1 also may offer favorable clinical efficacy of NTG-A-009 in the treatment of cancer." (PMID 29773813, 2018). "As IFN-γR is also expressed in cancer and directly connected to the same first neighbours (JAK1 and STAT1) as the cancer-related IL10R, IFN-γR may substitute the role of IL10R upon IFN-γ treatment." (PMID 28603644, 2017). "Considering the process of immune surveillance in cancer, it is likely that JAK1 mutant tumors are still recognizable to cells of the innate immune system (natural killer cells) or that JAK1 wildtype tumors have encountered other mechanisms to evade immune-mediated killing." (PMID 27213585, 2016). "In summary, hypomorphic recessive germline JAK1 mutations that affect multiple signalling pathways were found in a PID case that manifested with atypical mycobacterial infections and increased susceptibility to cancer." (PMID 28008925, 2016). "The present studies were undertaken to determine whether the myelo-proliferative disorder medication and JAK1/2 inhibitor ruxolitinib could be re-purposed as a cancer therapeutic against solid tumors." (PMID 26981780, 2016).
cancer (continued). "However, it is unknown whether the JAK1/2-STAT3 pathway is activated in ATC, and the anti-cancer effects and the mechanism of action of its inhibitor, ruxolitinib (Ruxo, a clinical JAK1/2 inhibitor), remain elusive." (PMID 38336839, 2024). "MiR23a and MiR27a suppress Jak1/Stat6 and Irf4/Ppar-γ of the Jak1/Stat6 pathway, respectively, again supporting how the Mir-23-27-24 clusters adopt a double-negative feedback loop in macrophage polarization networks, further providing evidence of their key regulatory activity in cancer progression." (PMID 38871817, 2024). "Therefore, therapeutic intervention intending to inhibit JAK1 expression in cancer cells may inadvertently inhibit the patient’s mast cell functions." (PMID 32275708, 2020). "JAK1, STAT1, and STAT3 expressions were stronger in PROC than in the platinum-sensitive group of primary chemotherapy-naive cancer tissues." (PMID 40883550, 2025). "We thus performed mass spectrometry analysis on cancer cells treated with TAK-243 to discover candidate targets and found that IFN pathway effectors, including JAK1 and IFNGR1, were stabilized by TAK-243 treatment." (PMID 39540840, 2025). "In summary, our findings uncover a previously unrecognized function of STING in regulating JAK1/STAT activation downstream of IFN-I stimulation and provide a new insight for future design and clinical application of STING agonists for cancer therapy." (PMID 39817453, 2025). "We examined the expression levels of cyclin B, Cdk1, cyclin D1, PCNA, JAK1, STAT3, and other cancer pathway components." (PMID 40350446, 2025). "This is achieved through the impairment of mitochondrial function and the inhibition of key signaling pathways, namely, Notch1 and JAK1/STAT3, which are critical drivers of cancer progression." (PMID 40019515, 2025). "A pivotal aspect of our research was the elucidation of the IL-11/JAK1/STAT4/CBP signaling axis and its role in the upregulation of c-MYC, marking a significant progression in cancer biology." (PMID 38429845, 2024). "Many studies have demonstrated that IL-6-specific functions in CAFs involve the IL-6/CXCR7 axis and the IL-6/Jak1/STAT3 axis, which play roles in the immune response, EMT and cancer cell migration." (PMID 39075612, 2024). "The interaction network of 50 SHP-1-binding proteins showed that many of them were involved in immune function and cancer signal transduction, such as IL4R, JAK1, CD33." (PMID 39367146, 2024). "They found that TPCA-1 was a dual inhibitor of both IKK-β and JAK1 kinase and confirmed that downregulation of type-I IFN pathways improves VSV replication and killing of resistant cancer cells." (PMID 39861805, 2024). "Altogether these data indicate that 4-OI promotes VSVΔ51 infection in cancer cells through the direct targeting of two critical proteins in the interferon signaling pathway, MAVS and JAK1." (PMID 38750019, 2024). "EGFR induces PD-L1 via the IL-6/JAK1/STAT3 pathway 63, which reciprocally drives PD-L1 phosphorylation (Tyr112) to evade cancer immunosurveillance." (PMID 38505617, 2024). "The expression cor-relationships between METTL3 and its targets, including JAK1, VEGFA, CCND1, and STAT3, was positive in almost all analyzed cancer types." (PMID 38001065, 2023). "On the contrary, some core kinases and transcription factors involved in cancer such as CDK6, ERBB2, JAK1, DAPK1, FOXO1, and RXRA were highly expressed in S-III." (PMID 38143770, 2023). "Interestingly, tofacitinib (JAK1 inhibitor) could reverse its cancer-promoting effects." (PMID 38094755, 2023). "A recent study suggested that the knockout of genes in the IFN γ receptor signal pathway (IFNGR1, JAK1, or JAK2) endowed solid tumor cells with resistance to CAR-T cells by reducing the overall binding time and affinity of CAR-T cells with the cancer cells." (PMID 37889543, 2023). "JAK1 is one of the JAK that phosphorylates proteins of the STAT family and plays a crucial role in multiple cancers, including GC." (PMID 36864711, 2023).
cancer (continued). "The same applies to JAK1, which acts as a key player for the JAK/STAT signaling pathway in the development and progression of several cancers." (PMID 38201452, 2023). "JAK1 is part of the JAK/STAT signaling pathway and is known as one of the central communication pathways for (cancer) cell function controlled by various cytokines and growth factors." (PMID 38201452, 2023). "Some kinases identified had lower kinase activity in cancer compared to normal tissue, amongst them Lmr1, EPHA7 and JAK1." (PMID 36093296, 2022). "IL22RA1 was positively correlated with STAT1, STAT3, JAK1, PTPN11, IFNA13, IL24, but negatively correlated with IL10 in specific cancers." (PMID 35874683, 2022). "Andrographolide is known to inhibit the actions of STAT3, JAK1, and JAK2 phosphorylation in human cancer cells." (PMID 35682652, 2022). "Janus kinases (JaK) are a family of tyrosine kinases (TKs), including JAK1, JAK2, JAK3, and TYK2, and all of their receptors actively participate in the pathogenesis of various human cancers." (PMID 35634509, 2022). "Cancer cells are known to secrete cytokines, including interferons, which in an autocrine manner can regulate the constitutive IDO1 expression via the JAK1/STAT1 signaling pathway." (PMID 35997090, 2022). "Momelotinib (CYT387), a JAK1 and JAK2 inhibitor, also showed strong anti-cancer activity by significantly reducing MM proliferation in preclinical results." (PMID 35503759, 2022). "In recent years, the Janus kinase 1/signal transducer and activator of transcription 3 (JAK1/STAT3) and extracellular signal-regulated kinase (ERK) kinase (MEK)/ERK signaling pathways have been widely reported to involve in cancer development." (PMID 35223991, 2022). "JAK1 is a member of the JAK protein family, which is closely related to the progression of various cancers." (PMID 34809653, 2021). "Excessive activation of EGFR activates multiple downstream signaling pathways, such as the MEK/ERK/MAPK, PI3K/AKT/mTOR, and JAK1/STAT3/5 signaling pathways), thereby enhancing the tumorigenesis, progression, and metastasis of various cancers." (PMID 33909822, 2021). "Previous research reported that JAK1/STAT3 signalling pathway was regulated by several growth factors, and subsequently contributes to cancer progression." (PMID 33523587, 2021). "CYT-low COAD tumors contained significantly more cancer genes harbored within chromothriptic regions (TCF12, NF1, ERBB2, JUN, JAK1 and BCL10)." (PMID 34316699, 2021). "STAT3, JAK1, and MYC are three oncogenes that have both anti-apoptotic and proliferative effects on cancer cells." (PMID 33391626, 2020). "Despite we have successfully identified a novel JAK1/2 inhibitor, like all the other JAKis, AH057 only inhibited cancer cell proliferation at relatively high concentrations." (PMID 32895373, 2020). "To evaluate if IST5 affects kinase activity in cancer cells, we tested kinase inhibitory activity of IST5 in two custom-tailored panels including 54 relevant kinases, including Jak1, Jak2, Jak3, Tyk2, Abl1, Abl2, Lck, Fyn, Src and TrkB/C." (PMID 33217941, 2020). "Cancer cells isolated from HCC patients and HCC cell lines showed clearly upregulated expression of circ9119 and Janus kinase 1 (JAK1) with decreased levels of miR-26a compared to healthy controls and normal hepatic cells." (PMID 32732872, 2020). "Momelotinib, an inhibitor of JAK1/JAK2, consistently abrogated the STAT5/LY6G6D axis in vitro, sensitizing MSS cancer cells with an intact JAK-STAT signaling, to efficiently respond to trametinib, a MEK inhibitor used in clinical setting." (PMID 30670049, 2019). "IL-6, JAK1, JAK2 and STAT3 which are considered main components of this pathway, have been found to be overexpressed in different cancers, including BCC." (PMID 31342143, 2019).
cancer (continued). "Through the analysis of copy number alteration of PM samples, we found that there were significant deletions in many genomic regions of PM samples, involving many cancer genes and immune related genes (such as B2M, RHOA, IFNE, JAK1/2, etc.)." (PMID 31570735, 2019). "We found that seven genes (ADPRH, IL1R1, KSR1, SOCS2, JAK1, NFAT5, and SSH1) were more highly expressed in the lower-TMB subtype than in the higher-TMB subtype of more than 10 cancer types." (PMID 30634925, 2019). "With CRISPR screening, multiple genes were also identified to be essential for cancer immunotherapy, including APLNR, which can interact with JAK1." (PMID 30294272, 2018). "Therefore, any stimulus which deregulates the expression of either JAK1 or TYK2 could potentially deregulate the entire type I IFN response signalling pathway and thereby weaken the immune system and thus predispose individuals to infections and or cancer." (PMID 28344639, 2017). "Overexpression of constitutively active STAT3 partly reversed the anti cancer effects of (−)-oleocanthal, which inhibited STAT3 activation by decreasing the activities of JAK1 and JAK2 and increasing the activity of SHP-1." (PMID 27259268, 2016). "After trastuzumab treatment, both AKT and ERK phosphorylation were less downregulated while Jak1 and STAT3 phosphorylation were unregulated more obviously in EGFRvIII+HER2+ than in EGFRvIII−HER2+ cancer cell lines." (PMID 26474285, 2015). "Type I IFN signaling (JAK1/2) inhibitor Ruxolitinib reversed the resistance, facilitating VSV replication in the macrophage-protected cancer cells." (PMID 28548066, 2014). "The expression level of six differentially expressed mRNAs (CUL2, HIF1A, RET, JAK1, STAT1, and BCL2) in the cancer pathway and two of their nearby lncRNA pairs (RP11-124O11.2 and lincRNA-TMEM30B-1) was verified by real-time quantitative RT-PCR (qRT-PCR)." (PMID 24672800, 2014). "To validate the correlation between STING and JAK1 in vascular endothelial cells in clinical databases, we performed a correlation study on endothelial signaling with JAK1-STAT1 signaling using the published datasets from tissues from patients with cancer." (PMID 39817453, 2025). "Firstly, tyrosine-protein kinase JAK1 is a non-receptor tyrosine kinase that regulates cytokine levels and participates in cancer, inflammatory, and autoimmune diseases." (PMID 41473273, 2025). "A new reported JAK1 mutation S404P, which near high-occupancy hydrogen bonds in the nonp JAK1 model, enhanced cancer cell invasion ability." (PMID 40868963, 2025). "These siRNA-target genes are mainly those that promote cell differentiation and proliferation and inhibit apoptosis, which are overexpressed in cancer cells, such as Bcl-2, survivin, epidermal growth factor receptor (EGFR), Janus kinase 1 (JAK1), and polo-like kinase 1 (PLK1)." (PMID 39407665, 2024). "Furthermore, we revealed hub gene JAK1 with huge impact in SCRS, which showed heterogeneous prognosis value in pan-cancer landscapes, suggesting potential research opportunities associated with senes CAFs." (PMID 39703515, 2024). "As predicted, HT55 and K2 failed to respond to IFN-γ compared with JAK1 WT cancer cell lines, as measured by failure to induce MHC-I and PD-L1 expression." (PMID 36669486, 2023). "F. nucleatum may enhance the expression of cancer-related genes and oncogenes including STAT3, JAK1, and MYC." (PMID 37174014, 2023). "It is also known that IL-6-activated Janus kinase 1 (JAK1) might lead to the phosphorylation of Y112 of programmed death ligand 1 (PD-L1) and consequently induce cancer immune evasion." (PMID 36385012, 2022). "Interestingly, andrographolide is known to inhibit the actions of STAT3, JAK1, and JAK2 phosphorylation in human cancer cells." (PMID 35682652, 2022).
cancer (continued). "Finally, JAK1 when activated phosphorylates STAT proteins, important for the expression of genes that mediate inflammation, epithelial remodeling, cancer progression and metastasis." (PMID 36313672, 2022). "JAK1 was one such gene identified as both TSG and OG in BRCA and COAD cancer types." (PMID 35620468, 2022). "Results show that the level of LEPROT was consistently positively correlated with that of JAK1, JAK2, and STAT3, which suggested that JAK1/2/STAT3 might be the downstream LEPROT and mediate cancer cell proliferation and TME alterations." (PMID 34804118, 2021). "In addition, IL20RA activates the Janus kinase 1 (JAK1)-STAT3-SOX2 signaling pathway, leading to increased expression of PD-L1 and reduced recruitment of anti-cancer lymphocytes, including CD8+ T cells and natural killer cells." (PMID 33456560, 2021). "For example, the expression of JAK1, which is located on chromosome 1p31.3, also had significant positive correlations with infiltrating levels of CD8+ T cells, CD4+ T cells, macrophages, neutrophils, and dendritic cells in cancer." (PMID 34335194, 2021). "Furthermore, let-7 participates in the JAK2/STAT signaling pathway in cancer cells by targeting SOCS4 and activates the JAK1/STAT3 signaling pathway." (PMID 34568312, 2021). "Collectively, these findings indicate that the inhibitory effect of IST5 on Stat5 phosphorylation in cancer cells is not due to inhibition of Jak2 or other key kinases including Jak1, Jak3, Tyk2, Src, Lck, Fyn, TrkB/C, Abl1 or Abl2." (PMID 33217941, 2020). "The observation that Fusobacteria upregulated STAT3, JAK1, and MYC indicated that Fusobacteria infection might enhance cancer cell survival through modulation of these oncogenes, which are well implicated in pathways that promote tumorigenesis." (PMID 33391626, 2020). "A similar data was previously reported in which Apigenin decreased the expression of phospho Janus Kinase 1/2 (phospho-JAK1/ JAK2), phospho-STAT3, and STAT3-dependent luciferase reporter gene activity in human epidermal growth factor receptor 2 (HER2)- expressing BT- 474 cancer cells." (PMID 32952942, 2020). "Interestingly, the JAK1/2 inhibitor enhanced the growth inhibitory effect of the MEK-inhibitor, particularly in poorly immunogenic BRAF or KRAS mutant cancer cells (HT29 and SW620)." (PMID 30670049, 2019). "MET-amplified cancer cells showed highly phosphorylated JAK1/2 kinases, while STAT1 was poorly or not active." (PMID 30723303, 2019). "More recently, Meads and collaborator demonstrated that PYK2 is positioned upstream of JAK1/STAT3 signaling and that it is a critical mediator of a novel survival pathway activated in the context of co-stimulation of cancer cell and the microenvironment through especially IL-6." (PMID 29455640, 2018). "The activated JAK1 and TYK2 in turn phosphorylate STAT1 and STAT2 setting in motion a cascade of events which finally initiates the transcription of IFN-inducible genes switching on the anti-cancer and anti-viral effects as reviewed in Randall and Goodbourn." (PMID 28344639, 2017). "In the first experiment, mice received subcutaneous injections of PBS or C26 cancer cells and were fed chow formulated with or without the JAK1/3 inhibitor R548 for 26 days." (PMID 26864813, 2016). "The potential role of apigenin as an anti-cancer agent was confirmed in HER2-overexpressing MCF-7 cells in which apigenin reduced tyrosine phosphorylation of HER2 and reduced expression of phosphorylated Janus kinase 1 (phospho-JAK1) and phospho-STAT3." (PMID 26694341, 2015). "In contrast, MEK inhibitor or JAK1/2 inhibitor as a single agent was not very effective on cancer cell viability." (PMID 25961376, 2015). "Many of these genes play important roles in a central pathway (the EGF/EGFR/JAK1/AKT/NF-κB axis) that might lead to the survival and proliferation of cancer cells." (PMID 22479575, 2012).